CSF1 (colony stimulating factor 1)
Diseases named in the same sentence as CSF1 in open-access papers (continued):
Sharing a sentence is not in itself a finding about the gene and the disease.
tumor (continued). "For example, by secreting an abundance of pro-tumorigenic proteases, cytokines and growth factors, TAMs support a variety of behaviors within the primary tumor, such as growth, angiogenesis and invasion (e.g., EGF, which participates in a paracrine signaling loop via tumor-secreted CSF-1)." (PMID 36139552, 2022). "Blocking CSF-1/CSF-1R alone increased PD-1/PD-L1 expression on TAM cells and CTLA-4 expression on CD8+ T cells, whereas combination with PD-1 or CTLA-4 antagonists led to more significant T cell infiltration and tumor regression." (PMID 35874717, 2022). "Our study showed that CSF1 expression was present in 50 of 65 (77%) TSGCT cases by IHC in which many CSF1-positive cells were scattered in the tumor and discernable cytoplasmic staining was seen regardless of its intensity." (PMID 36320082, 2022). "We presented a case of GCTTS in the breast after augmentation and concluded that the pathogenesis of this tumor based on synovial metaplasia was independent of classical CSF1 translocation." (PMID 35814458, 2022). "In addition to inhibition of CSF‐1‐CSF‐1R, CCL2‐CCR2, and CCL5‐CCR5 axes, amelioration of tumor hypoxia can also reduce the recruitment of macrophages." (PMID 37323705, 2022). "As a major activator of TAM phenotypes in tumor microenvironment, IL-4 supplied by either T cells or tumor cells can act on TAMs to up-regulate cathepsin enzyme activity in TAMs and augment the EGF/CSF-1 paracrine loop between TAMs and tumor cells." (PMID 35996149, 2022). "On the other hand, it was reported that there was an interaction between the tumor grade and the stroma in PDAC tissues, where low grade PDAC cells maintain activated stroma by reduced expression of CSF-1, suggesting that these PDAC cells benefit from the activated stroma-derived signals." (PMID 35272688, 2022). "This review summarizes the immune checkpoint and other receptor-ligand interaction between macrophages and tumor cells, which plays an indispensable role in anti-tumor immunity or pro-tumor immunity, such as SIRPα-CD47, PD1-PD-L1, FcγR-Antibody-Antigen, CSF-1/CSF-1R axis." (PMID 36497444, 2022). "TAMs originate from peripheral blood monocytes that infiltrate into the tumor microenvironment in response to cytokines such as VEGF, colony stimulating factor-1 (CSF1), CXC motif chemokine ligand-12 (CXCL12) and various CC motif chemokine ligands (CCL) such as CCL2." (PMID 36421358, 2022). "Moreover, the secretion of factors such as Colony-Stimulating Factor 1 (CSF1) by tumor cells and surrounding macrophages, as well as NRGs, can significantly influence tumor growth and resistance." (PMID 35158804, 2022). "By contrast, cases negative for CSF1 on IHC exhibited no or only 2% CSF1 split signal of tumor cells." (PMID 36320082, 2022). "Recently, it has been demonstrated that hybrid E/M cells induce the formation of a tumor-promoting microenvironment through the upregulation of potent immunosuppressive proteins, including PD-L1, CD73 (5′-NT), CD276 (B7-H3), CSF1 (M-CSF), SPP1, galectin-3, MASP1, and SDF1 (CXCL12)." (PMID 36467417, 2022). "Western blot confirmed high levels of CSF1 and CCL14 protein in UHRF1 expressing tumor cells." (PMID 35664070, 2022). "Notably, CSF-1 has autocrine and paracrine manners in the TME, which adds a new layer of CSF-1R’s tumor-promoting role in malignant tumors." (PMID 35444953, 2022). "Macrophages are a major component in the tumor microenvironment arising from spinal marrow-derived monocyte differentiation in response to CC chemokine 2 (CCL2/CCR2) and colony-stimulating factor 1 (CSF-1/CSF-1R)." (PMID 36246916, 2022). "Unsupervised clustering on the expression profiles issued from this series suggested two distinct subgroups: one composed of various molecular subtypes including CSF1 and FN1 rearranged samples and one composed of four tumors harboring an HMGA2::NCOR2 fusion, suggesting distinct tumor entities." (PMID 36439507, 2022).
tumor (continued). "As already mentioned, TAMs are a heterogeneous population that includes resident cells of embryonic origin present at birth and invading monocytes/macrophages recruited during early carcinogenesis by chemokines secreted by tumor and stromal cells (such as CCL2, CCL5, and CSF-1)." (PMID 35183252, 2022). "Moreover, in a pancreatic cancer mouse model, blocking of CSF-1/CSF-1R reduced M2 macrophages within the TIME and polarized the remaining TAMs into an anti-tumor phenotype." (PMID 35874717, 2022). "Therefore, CSF1 expression is a characteristic finding of TSGCT, and CSF1 expression leads to the recruitment of macrophages to the tumor tissue of osteoclast-like giant cells." (PMID 36320082, 2022). "When a tumor develops, it can recruit and induce macrophages in the TME with various chemokines and cytokines, such as CXCL12, CCL2, GM-CSF, colony-stimulating factor 1 (CSF-1), and IL-3." (PMID 35205732, 2022). "In addition, estrogen receptor beta (ERβ) agonist LY500307 reduced tumor-derived CSF1 and decreased infiltration of CSF1R+ MDSCs in the tumor bed." (PMID 35003065, 2021). "As CSF1 and FGF signals are both involved in the accumulation of tumor-infiltrating/promoting MDSCs and M2-TAMs, the dual inhibition of FGF and CSF1 or VEGF signaling is expected to enhance antitumor effects through the targeting of immune evasion and angiogenesis in the TME." (PMID 34502435, 2021). "The oral administration of PLX3397 (Turalio®) has been approved by the U.S. Food and Drug Administration (FDA) for the treatment of unresectable tenosynovial giant cell tumor, which is a rare and locally aggressive non-malignant tumor that overexpresses CSF-1." (PMID 33802565, 2021). "In CSF‐1‐knockout MMTV‐PyMT+/‐ spontaneous breast cancer mice, the perivascular macrophage density was declined with a sixfold reduction, accompanied by a 16‐fold decrease of circulating tumor cells in the blood." (PMID 33463063, 2021). "Since tumor-induced exclusion/immunosuppression involves the activation of multiple signaling pathways, pharmacological inhibition would be effective in this regard, including pathways of Wnt/β-catenin, PI3K-Akt, IFN-β/NOS2, CSF-1, TGF-β, adenosine, and IDO." (PMID 34194441, 2021). "In addition, overexpression of SPON2 enhanced, while knockdown of SPON2 reduced IL10, CCL2 and CSF1 expression levels and secretion in CRC tumor cells." (PMID 34583750, 2021). "It has been reported that miR-125b is downregulated in TGCT and that low levels are associated to increased production of tumor-derived chemokine CSF1 and CX3CL1, which are known to control the recruitment of macrophages to the neoplastic sites that in turn stimulate tumor growth." (PMID 34440480, 2021). "Homozygous null CSF1 MMTV-PyMT mice exhibited a remarkable decrease in tumor progression to advanced disease and lacked evidence of pulmonary metastasis." (PMID 33235291, 2021). "Tumoral chemotaxis of these immune cells is mediated by chemoattractants such as chemokine ligand 2 (CCL 2, 5, 7, 8, 22), CXCL 8 and 12, PDGF, VEGF, endothelial monocyte-activating polypeptide (EMAPII), and colony-stimulating factor-1 (CSF-1)." (PMID 34138386, 2021). "Subsequently, the tumor cell microenvironment was filled with abundant growth factors and inflammatory mediators [colony stimulating factor-1 (CSF-1), IL-4, IL-10, and TGF-β], which changed the phenotype of macrophages into M2-type macrophages with the function of promoting tumor growth." (PMID 34950700, 2021). "Furthermore, TECs are capable of expressing various growth factors, including CSF-1, VEGF, and PDGF under tumor hypoxia." (PMID 33230600, 2021). "Ex vivo primary FL-FDC co-cultures (n = 19) and in vivo mouse co-xenografts demonstrated that FL-FDC crosstalk favors tumor growth and, via the secretion of CCL2 and CSF-1, promotes monocyte recruitment, differentiation, and polarization towards an M2-like protumoral phenotype." (PMID 33731849, 2021).
tumor (continued). "Likewise, combining CSF1/CSF1R inhibitors with immunotherapies including anti-PD1 and anti-CTLA4 induces a synergistic effect and induces potent tumor regression in experimental models of PDAC." (PMID 34201127, 2021). "The recruitment of bone marrow-derived monocytes, which differentiate into TAMs, is driven by circulating mediators released by both tumor and stromal cells, including cytokines (IL-1β, IL-10, IL-13, IL-34), osteoactivin, VEGF-A, and colony stimulating factor-1 (CSF-1)." (PMID 33922362, 2021). "Secreted CSF1 increases MMP2 and VEGF-A expression in TAMs, promoting tumor angiogenesis." (PMID 33406733, 2021). "Moreover, components of the CSF1/CSF1R axis are highly expressed in gastric cancer and promote tumor proliferation and migration." (PMID 33406733, 2021). "Interestingly, expression of colony stimulating factor 1 (CSF1), CSF2, CSF3, C-C motif ligand 2 (CCL2), CCL7, and C-X-C motif ligand 2 (CXCL2), which promote myeloid cell recruitment and drive tumor progression, was dependent on RelB." (PMID 34198987, 2021). "Furthermore, in vitro co-culture models have shown that tumor cell-macrophage co-culture induced M2-like polarization via increased expression of IL-10, IL-12, IL-6, TNF-α, CCL5, CCL22, and CSF1." (PMID 34439281, 2021). "Looking into detail in each of these categories, genes previously related to bone tropism were found to be overexpressed in PC3-BM cells, such as CXCR4 and its ligand CSF1, as well as CCL2, all of them directly involved in signaling pathways regulating circulating tumor cells (CTCs) homing to bone." (PMID 34944822, 2021). "Interestingly, TAMs are mobilized to the peripheral blood and then recruited in the PMNs by many tumor-secreted cytokines and growth factors (e.g., CCL2, CSF-1, VEGF, PLGF, TNF-α, TGF-β), tissue inhibitor of metallopeptidase (TIMP)-1, and exosomes." (PMID 33916915, 2021). "For instance, tumor cell-derived C-C motif chemokine ligand 2 (CCL2) and colony stimulating factor 1 (CSF1) lead to increased infiltration of macrophages in the tumor microenvironment (TME), which, in turn, enhances angiogenesis by inducing vascular endothelial growth factor (VEGF) expression." (PMID 34207286, 2021). "Furthermore, experiments using co-cultured tumor cells and macrophages showed augmented expression levels of IL10, IL12, IL6, TNF, CCL5, CCL22, and CSF1 in macrophages, which facilitated M2-like polarization." (PMID 34207286, 2021). "The alternatively activated pathway, in the presence of Th2-derived cytokines such as IL-4, IL-10, IL-13, TGF-β, prostaglandin E2, or colony stimulating factor 1 (CSF1), gives rise to the M2-like macrophage phenotype, which typically facilitates tumor progression." (PMID 34204306, 2021). "For example, in ongoing clinical trials targeting CSF-1, anti-CSF-1R monoclonal antibodies (such as IMC-CS4 in NCT01346358) block the binding of CSF-1 and IL-34 to CSF-1R and abrogate the recruitment and survival of TAMs, leading to TAM apoptosis and inhibition of tumor growth." (PMID 34683963, 2021). "Such a macrophage polarization was also shown by hypoxic tumor exosomes enriched in CCL2, CSF1, TGF-β, macrophage migration inhibitory factor (MIF), ferritin heavy/light chain, endothelial monocyte-activating polypeptide 2 (EMAP2), and leukotriene A-4 hydrolase." (PMID 32499786, 2020). "CSF1 might negatively regulate inflammatory responses by activating PI3K230, and CSF1R is expressed on both tumor-suppressing and tumor-promoting myeloid cells." (PMID 32801364, 2020). "Chemokines secreted by tumor cells, such as CCL2 and CSF1, recruit and polarize monocytes." (PMID 32983125, 2020). "We found that Csf1 was highly expressed in ID8 and B16 tumor cells." (PMID 32286255, 2020). "To date, various signaling pathways, including PGE2, CCL2, CSF-1, TGF-β, CXCL5, CXCL12, IL-1β, and IL-6, have been identified to be involved in the infiltration and activation of MDSCs in tumor microenvironment." (PMID 32824865, 2020).
tumor (continued). "In vitro analysis revealed that PPF did not exert its effects on the CSF-1 cell line, rather its anti-tumor effects were attributed to its effect on microglial migration and the contribution of microglia to tumor cell migration." (PMID 33178210, 2020). "Endothelial cells, pericytes, and TAMs contribute to tumor intravasation by performing pro-angiogenic effects; conversely, VEGF, colony-stimulating factor-1 (CSF-1), and Ang2 induce neo-vessel formation via the expression of interleukin 8 (IL-8) in murine cancer models." (PMID 32974184, 2020). "Reintroduciton of mCcl2, Csf-1, and mCtnnb1 into ID8/Ubr5−/− cells enhanced TAM recruitment, accelerated spheroid proliferation and colonization, and partially but significantly restored tumor growth." (PMID 33293516, 2020). "Cytokines released from tumor-residing cells including tumor cell–derived IL-4, IL-10, CCL2, CCL3, CCL4, and CSF1; Treg-derived IL-10; B cell–produced immunoglobulins; Th2-derived IL-4 and IL-13; and MSC-derived MFG-E8 promote the polarization into a protumor phenotype." (PMID 31256327, 2020). "We found that CCL2, but not CSF-1 produced by tumor cells is highly expressed by high-grade lesions, thus highlighting the role of this chemokine in the recruitment of suppressive BMDMs." (PMID 32642721, 2020). "By blocking the CSF-1 signaling in combination with anti-VEGFR2 therapy, tumor growth could be markedly decreased in murine lung carcinoma models." (PMID 33469537, 2020). "CSF1, also known as macrophage colony stimulating factor (MCSF), is a cytokine that acts as growth factor and differentiation factor for myeloid cells and at least for some tumor cells." (PMID 31731509, 2019). "Some cytokines, chemokines or growth factors such as tumor growth factor-β (TGF-β), the chemokine C-C motif ligand 2 (CCL2), colony-stimulating factor 1 (CSF-1), C-X-C motif chemokine ligand 12 (CXCL12), or insulin-like growth factor 1 (IRF1) are induced by RT in the tumor environment." (PMID 31179236, 2019). "Therefore, inhibition of either CSF-1 or EGF signaling pathway perturbs the migration of both cell types and reduces the numbers of circulating tumor cells as well." (PMID 31300030, 2019). "Additionally, hypoxia can also promote TAMs to infiltrate in the inner region of the tumor by secreting chemokines such as chemokine C-C motif ligand 2 (CCL2), CCL5 and CSF-1." (PMID 31629410, 2019). "Neutralizing anti–CSF-1R and anti–CSF-1 antibodies, or small-molecule inhibitors of CSF-1R, not only left the tumor growth unaffected but actually increased spontaneous metastasis." (PMID 31406165, 2019). "We found that the CSF-1 expression was positively correlated with tumor size (P = 0.04, data not shown)." (PMID 31565097, 2019). "Tumor-initiating cells with YAP hyperactivation recruit M2 macrophages at the early phases of cancer development, mainly through direct YAP–TEAD targeting of CCL2 and CSF1 (colony stimulating factor 1)." (PMID 31052239, 2019). "Based on the development of a number of small-molecule and antibody antagonists to prevent receptor dimerization, current research is thereby focused on abrogating binding to CSF1 and activation of signaling, decreasing TAM infiltration and augmenting the effect of antitumor immune in the tumor." (PMID 31805946, 2019). "In general, increased T‐cell numbers follow CSF‐1(R) blockade in a variety of tumour models, but rarely results in growth inhibition without additional therapies." (PMID 30442705, 2018). "Intravital imaging in tumor-bearing mice showed that dextran-labeled TAMs expressing CSF-1 receptor and GFP-labeled tumor cells expressing EGF receptor co-migrated toward microneedles containing either EGF or CSF-1." (PMID 29599778, 2018). "H-RS cells secrete Colony Stimulating Factor-1 (CSF-1) and macrophage migration inhibitory factor (MIF) to recruit M2 macrophages, which in turn, secrete chemokines like, IL-8, to attract neutrophils into and eotaxin to attract eosinophils into tumor tissue." (PMID 30101129, 2018).
tumor (continued). "Together, these data suggest that a miRNA network combinationally targeting the core regulons (e.g., CSF1, CX3CL1) may be guaranteed by miR-125b in NCCIT tumor cells." (PMID 30237497, 2018). "Tumor-derived soluble mediators such as chemokines (CCL2, CCL5, CXCL12), colony-stimulating factor-1 (CSF-1), TGF-β, IL-10, prostaglandin E2 (PGE2) and metabolites (lactate) likely contribute to the development of TAMs with M2-like phenotype and tumor-promoting properties." (PMID 30563569, 2018). "CSF-1 induces the differentiation commitment of myeloid progenitor cells to non-classic M2 macrophages, which in general play a tumor suppressive role by inhibiting T cell functions in the tumor microenvironment." (PMID 29930294, 2018). "In the tumor microenvironments, there are not only IFN-γ, TNF-a, and GM-CSF which could activate macrophages like M1 macrophages, but also IL-4, IL-10 and CSF-1 which induce M2 macrophages differentiation." (PMID 30180849, 2018). "To formally test whether tumor-derived CSF-1 was responsible for inducing TAM RAE-1δ, we used CRISPR/Cas9 to target the Csf1 open reading frame for deletion in B16 cells." (PMID 29757143, 2018). "Furthermore, it was recently shown that ADT stimulates tumor cells to produce macrophage colony stimulating factor-1 (M-CSF1), leading to increased TAM infiltrates in both PCa patients and tumor-bearing mice." (PMID 28134800, 2017). "Tumor-derived chemokines, including CCL2 and CSF1, recruit peripheral monocytes to the tumor site." (PMID 28467800, 2017). "Some other microenvironmental factors such as CSF-1, CCL2, IL6, vascular endothelial growth factor (VEGF-A) and platelet-derived growth factor (PDGF) have also been involved in infiltration of monocytes to the tumour sites." (PMID 29065107, 2017). "This massive recruitment of TAMs is usually facilitated by chemokines like CCL2, CCL5, VEGF, CSF-1, semaphorin 3A (SEMA3A), endothelin, eotaxin and oncostatin M. Once macrophages arrive in these tumour compartments, their migration is halted via hypoxia-dependent mechanisms." (PMID 29065107, 2017). "These monocytic MDSCs migrate to tumor microenvironment mainly by CCL2 and CSF-1 signaling and may differentiate locally into TAMs." (PMID 28197019, 2017). "Notably, the attack of tumor cells via chemotherapy or irradiation induced an upregulation of tumor-derived CSF1 secretion followed by enhanced TAM infiltration that provided additional growth and survival factors for the tumor." (PMID 28716061, 2017). "Because recruitment of TAMs to target vessels to induce vascular permeability requires CCL2 and colony-stimulating factor 1 (CSF1) synthesized by tumor cells to target receptor CCR2 and CSF1R on TAMs, inhibition of CCR2 or CSF1R signaling reduces tumor growth and metastasis." (PMID 28467800, 2017). "Similar to observations in hemorrhagic areas of the tumor, the presence of RBCs increased mRNA expression of Cxcl1 (KC), Cxcl2 (MIP-2), and Csf1 (M-CSF), suggesting that the activation of macrophages by heme/iron may trigger recruitment of myeloid cells." (PMID 29167669, 2017). "The CSF1/CSF1R pathway is critical in recruiting TAMs and promoting tumor growth." (PMID 28348554, 2017). "Mechanistic studies revealed that DNA damage-induced kinase ABL1 enhanced CSF-1 expression, while selective inhibition of its receptor kinase CSF1R (CD115) by GW2850 or PLX3397 inhibitors hampered TAM recruitment and suppressed tumor growth in murine prostate and thyroid cancer models." (PMID 27886105, 2016). "Recently it was shown that blocking the recruitment of macrophages using antibody blockade of CSF1 or CSF1R antagonism with the small molecule inhibitor PLX3397, which is being evaluated clinically, resulted in a CD8 T cell dependent reduction in tumor burden in the MMTV-PyMT model." (PMID 27066484, 2016). "As demonstrated in several malignancies including CRC, overexpression of CSF1 and CCL2 may result in accelerated tumor progression and poor prognosis." (PMID 26799669, 2016).